ZNF217 (zinc finger protein 217)
Diseases named in the same sentence as ZNF217 in open-access papers (continued):
Sharing a sentence is not in itself a finding about the gene and the disease.
cancer (continued). "ZMYND8 gene is localized at chromosomal region 20q13, which also contains candidate breast cancer oncogenes: MYBL2 (MYB proto-oncogene like 2), ZNF217 (zinc finger protein 217), and AURKA (aurora kinase A)." (PMID 28055972, 2017). "To elucidate the underlying mechanism by which ZNF217 exerts its function in iron-related cancer growth, we assessed the FPN expression upon ZNF217 downregulation or upregulation." (PMID 27768596, 2016). "Of these chromosome 20 genes, only ZNF217 (FDR 2.67e-2, cancer/normal ratio 1.57) and AURKA (FDR 5.52e-5, cancer/normal ratio 2.32) were also significant in the LCM data set." (PMID 19419571, 2009). "Candidate oncogenes, ZNF-217, CYP24A1, MYBL2 and AIB2, encompassing the region analyzed by FISH, were previously reported to be amplified in other types of cancer as well." (PMID 17311676, 2007). "ZNF217’s oncogenic activity is dependent on its ability to bind DNA and alter multiple processes, including EMT, that are critical in driving different aspects of cancer progression." (PMID 41345234, 2025). "In addition, we found that CoREST and LSD1 exhibit highly significant co-dependency with ZNF217 in genome-wide CRISPR KO screens across 1,139 cancer cell lines." (PMID 40093906, 2025). "Our findings indicated that ZNF217 played a more critical role in the survival of B-ALL cell lines compared to non-B-ALL cancer cell lines." (PMID 40093906, 2025). "Further, the previous report did not investigate the effect of ZNF217 depletion in cancer cells nor address ZNF217’s effect on immortalized primary cells and therapeutic response in cancer cells." (PMID 41345234, 2025). "Previous studies have suggested that genes located in this region, such as ZNF217, GPC3, and CYP2S1, could contribute to the development and progression of cancer." (PMID 40354349, 2025). "Although other members of this family, such as ZNF224 and ZNF217, play important roles in cancer development, the role of ZNF286A has not been studied in any disease." (PMID 36134026, 2022). "We also detected differentially methylated regions in cancer-related genes, such as CMYA5, TSLP, ZNF503, and ZNF217, which suggest that the methylation status of these genes may be involved in tumorigenesis or cancer progression." (PMID 34527193, 2021). "Considering the accumulating evidence that ZNF217 plays an essential role in tumor progression, metastasis, and chemoresistance, it is predictable that ZNF217-regulated m6A modification, possibly by interaction with METTL3, is relevant in human cancers." (PMID 30149601, 2018). "Over-expression of SALL4 and ZNF217 were negatively correlated with clinical prognosis of 3-year, 5-year, 10-year and disease-free survival in solid malignancies, irrespective of cancer types, source regions, mean-age and sex predominance." (PMID 27007163, 2016). "Therapies targeting ZNF217 could be promising in cancer treatment; however, the lack of identification of the full 3D structure of ZNF217 incites investigation of mechanisms of regulation of ZNF217 to delineate alternative candidate therapeutic strategies." (PMID 36551531, 2022). "ZNF217, an m6A methyltransferase inhibitor, interacts with some epigenetic regulators, activates the transcription of key pluripotency genes, regulates m6A deposition on their transcripts via sequestering METTL3 28 and is involved in the proliferation, survival and invasiveness of cancer cells." (PMID 32961012, 2020). "Exposure to hypoxia also induces ZNF217 (zinc finger protein 217)-dependent inhibition of m6A methylation of NANOG and KLF4 transcripts, both important pluripotency factors that mediate CSC maintenance, in turn, influencing cancer radiosensitivity and recurrence." (PMID 29439529, 2018). "In addition to imprinted genes, the 20q11-q13.32 chromosomal region contains multiple non-imprinted genes involved in cancer, e.g., AIB3, AIB4, AURKA (STK6), BTAK, MYBL2, PTPN1, STK15, and ZNF217." (PMID 36461044, 2022).
tumor (52 papers, 2007 to 2025). "We and others recently reported recurrent mutations in the CoREST-binding protein ZNF217 in tumor samples from patients with primary mediastinal B cell lymphoma (PMBCL), gray zone lymphoma and Hodgkin lymphoma (HL) with the highest prevalence in PMBCL (~30%)." (PMID 37648814, 2023). "In BCa tumor samples, high expression levels of ZNF217 are associated with shorter relapse-free survival, while high miR-503 levels are associated with improved survival." (PMID 36551531, 2022). "High mRNA levels of ZNF217 or LSD1 were associated with bad prognosis in HCC tumor patients, while high miR-101 levels were associated with better overall survival, supporting the clinical relevance of the findings." (PMID 36551531, 2022). "We report for the first time that high ZNF217 mRNA expression level measured by RT-qPCR in the initial tumor samples (pre-treatment) is associated with poor response to neoadjuvant ET." (PMID 30740056, 2018). "Although we and other studies have identified the effect of ZNF217 on tumor behaviors, the mechanisms underlying abnormal ZNF217 in iron-related tumors growth remain unexplored." (PMID 27768596, 2016). "Both ZNF217 protein and mRNA tumor expression have been associated with 20q13 copy number for several tumor types." (PMID 27363029, 2016). "Additionally, responses were observed in patients with low tumor mutation burden and ZNF217 mutation." (PMID 39712455, 2025). "Responses were observed in patients with low tumor mutation burden and ZNF217 mutation." (PMID 39712455, 2025). "Our in vitro and in vivo experiments have demonstrated that FOS suppresses B-ALL leukemogenesis and serves as a bona fide tumor-suppressor downstream target of ZNF217 in B-ALL." (PMID 40093906, 2025). "Consistent with its effect on tumor progression, ZNF217 exerted a dose-dependent effect on survival." (PMID 41345234, 2025). "In prostate cancer cells, ZNF217 decreased ferroportin concentration leading to increased intracellular iron retention, and iron-dependent cellular activities that enhanced tumor growth." (PMID 41345234, 2025). "Mice injected with ZNF217-Hi OVCA420 cells had a significantly larger tumor burden within the peritoneal space compared to mice injected with control cells." (PMID 41345234, 2025). "As in Foxn1 mice, in an NSG i.p injection model using OVCA420 cells, ZNF217 overexpression resulted in increased metastasis, higher tumor burden, and decreased survival." (PMID 41345234, 2025). "Our in vivo data collectively establishes that ZNF217 is a powerful oncogene that can promote tumor progression and metastasis in a dose-dependent manner if its levels are elevated at either early or later stages in the metastatic process." (PMID 41345234, 2025). "Consistent with ZNF217’s ability to promote aggressive metastasis and increase tumor burden, ascites fluid accumulated in mice bearing ZNF217 overexpressing tumors." (PMID 41345234, 2025). "Consistent with ZNF217’s ability to drive aggressive metastatic tumor formation, i.p injection of ZNF217 overexpressing cells resulted in a striking decrease in survival in Foxn1 nude mice." (PMID 41345234, 2025). "miR-135 is a tumor suppressor, which can target and negatively regulate ZNF217, thereby promoting the m6A modification of NANOG and reducing its expression." (PMID 37901333, 2023). "All those studies highlight the importance of fully understanding the wide diversity of epigenetic mechanisms regulating EMT-TF, such as ZNF217, with the ultimate aim to design therapeutic strategies counteracting tumor progression and metastasis development." (PMID 36551531, 2022). "On the other hand, the ZNF217 protein controls gene expression signatures and molecular signaling for tumor progression by tuning DNA methylation status at key promoters by interfering with noncoding RNAs or by refining the epitranscriptome." (PMID 36551531, 2022).
tumor (continued). "On the other hand, ZNF217 has been also reported to negatively regulate the expression of tumor-suppressive lncRNAs." (PMID 36551531, 2022). "In HCC, silencing ZNF217 inhibited cell proliferation in vitro and tumor growth in mice xenograft, whereas its enforced expression promoted EMT and HCC cell invasion." (PMID 36551531, 2022). "The present review focuses on and discusses recent advances delineating the complex interaction between ZNF217 and epigenetic processes to orchestrate tumor progression." (PMID 36551531, 2022). "The same study showed that ZNF217 mRNA is a direct target for miR-101, a well-reported tumor suppressor in HCC." (PMID 36551531, 2022). "Supportive in vivo experiments validated the oncogenic role of the CTBP1-AS2/miR-3163/ZNF217 axis in accelerating tumor growth." (PMID 36551531, 2022). "Until now, the intrinsic regulatory mechanisms of ZNF217 exerts its oncogenic activity are still elusive, and only a few targets have been verified in tumor cells." (PMID 27768596, 2016). "In contrast, decreased of ZNF217 expression restrained tumor cell growth by promoting FPN-driven iron egress." (PMID 27768596, 2016). "These combined data demonstrated that aberrant ZNF217 expression modulates iron-related tumor cell growth." (PMID 27768596, 2016). "Consistent to in vitro results, tumor growth and the final mean volume of the xenograft tumors (6/10) were substantially inhibited almost 50% in ZNF217 knockdown group, when compared with those in control group (8/10) (P<0.05)." (PMID 27768596, 2016). "ZNF217 has been shown to interfere with the apoptotic pathway at early stages of tumor progression, by impairing apoptotic signals resulting from dysfunctional telomeres, and in later stages, by conferring resistance to chemotherapy." (PMID 26431164, 2015). "In conclusion, accumulating data indicate that ZNF217 is a key player in tumorigenesis, orchestrating tumor progression at both early and late stages." (PMID 26431164, 2015). "We found that high ZNF217 expression consistently predicted poor prognosis across multiple tumor subtypes: Luminal, ER−, HER2+/ERBB2+, and basal cohorts." (PMID 24962896, 2014). "Our recent studies show the overexpression of ZNF217 promotes cell plasticity particularly in the maintenance of the de-differentiated stem-like cell state, and accelerates tumor progression and metastasis." (PMID 24962896, 2014). "Densitometry indicated a high correlation for ZNF217 and ERα protein expression (r2 = 0.93) in the tumor samples." (PMID 24962896, 2014). "The two chromosomes contain oncogenes, c-myc (v-myc myelocytomatosis viral oncogene homolog; 8q24.12) and ZNF217 (zinc finger protein 217; 20q13.2), which are relevant to various types of tumor." (PMID 24649216, 2013). "A significant increase in tumor growth was observed in mice injected with ZNF217-1 cells as compared with those receiving control cells." (PMID 21059223, 2010). "To determine how ZNF217’s oncogenic effects translate to an in vivo setting and to ascertain if ZNF217 exerts a dose-dependent effect on tumor progression, we derived luciferase-tagged OVCA420 cells that stably expresses low (ZNF217-Lo) and high (ZNF217-Hi) levels of FLAG-tagged ZNF217." (PMID 41345234, 2025). "Our data shows that ZNF217 promotes multiple aspects of tumor progression and metastasis, such as, cell proliferation and migration, ability to reorganize ECM, attach to ECM proteins and invade, resist anoikis to form multicellular aggregates, and chemo-resistance." (PMID 41345234, 2025). "Notably, ZNF217-Hi cells were more aggressive in forming tumors compared to ZNF217-Lo cells suggesting that ZNF217 exerts a dose dependent effect on tumor progression." (PMID 41345234, 2025). "Furthermore, HE staining and immunohistochemical analyses of the bone, liver, and spleen tissues revealed a notable reduction in tumor cell infiltration and decreased expression of ZNF217, Ki67, and C-MYC in bone/liver/spleen tissues." (PMID 40083704, 2025).
tumor (continued). "Additionally, FOS acts as a critical tumor-suppressor and CoREST-independent target of ZNF217 in B-ALL." (PMID 40093906, 2025). "In addition, miR-135 effectively suppressed tumor growth and metastasis in vivo by down-regulating ZNF217/NANOG." (PMID 37901333, 2023). "Additionally, mir-203 targets roundabout guidance receptor 1 (ROBO1) mRNA, which codes for a well-known tumor suppressor, thus possessing opposite effects than those of the ZNF217 oncogene." (PMID 36551531, 2022). "Furthermore, in vitro and in vivo experiments highlighted that miR-135 impedes EMT in BCa cells and suppresses in vivo tumor growth and metastasis via disruption of the ZNF217/NANOG axis." (PMID 36551531, 2022). "Moreover, ZNF217 is capable of promoting tumor cell invasion and metastasis through inhibiting E-cadherin expression in tumor cells." (PMID 36358661, 2022). "Future work is, thus, needed to decipher whether lncRNA SNHG1/ZNF217 regulatory circuits also participate in tumor progression." (PMID 36551531, 2022). "On the other hand, ZNF217 could control gene expression signatures and molecular signaling for tumor progression and cell plasticity." (PMID 36551531, 2022). "Nevertheless, since the original description, the ZNF217-ΔE4 variant has never been studied, either in terms of expression in human tumor samples or in terms of biological relevance." (PMID 34277402, 2021). "Interestingly, ZNF217-ΔE4 mRNA levels were significantly correlated with those of ZNF217-WT in tumor samples." (PMID 34277402, 2021). "Additionally, the levels of CTBP1-AS2 and ZNF217 were lower in tumor tissues removed from mice in sh-CTBP1-AS2#1 group than that in sh-Ctrl group." (PMID 32742190, 2020). "Rescue experiments results manifested that ZNF217 overexpression could abolish the anti-tumor ability of sh-CTBP1-AS2." (PMID 32742190, 2020). "ZNF217 up-regulation abrogated the tumor suppressing effects of CTBP1-AS2 knockdown." (PMID 32742190, 2020). "Consistent with the AKT signaling pathway being a potential target after ZNF217 overexpression, our lab identified the Akt inhibitor triciribine as the only drug tested in vivo that has shown the potential to decrease tumor burden in a human breast xenograft with high ZNF217 expression." (PMID 29312549, 2017). "We used patient-derived tumor xenografts grown in immune compromised NOD SCID mice to determine the efficacy of TCN→PAC compared to PAC→TCN on tumors of human origin that also overexpress ZNF217." (PMID 29312549, 2017). "Interestingly, we found that tissue iron content in tumor samples was significantly decreased in ZNF217 knockdown group, compared to those of control group (P<0.05)." (PMID 27768596, 2016). "Moreover, tissue iron concentration in tumor samples was obviously elevated in ZNF217 overexpressed group (P<0.05)." (PMID 27768596, 2016). "Besides, we found that overexpression of ZNF217 significantly promoted tumor growth, with the mean weight of xenograft tumors increased almost 2.6-fold in ZNF217 overexpression group (8/10) than control group (6/10) (P<0.05)." (PMID 27768596, 2016). "In addition, elevated myc-associated zinc finger protein (MAZ) levels transcriptionally promotes ZNF217 expression in tumor cells." (PMID 27768596, 2016). "Furthermore, we also uncovered that elevated ZNF217 significantly inhibited FPN expression to enhance the demand of iron in tumor cells." (PMID 27768596, 2016). "We screened a small sample size of 15 tumor lysates and immunoblotted for ZNF217 and ERα." (PMID 24962896, 2014). "Furthermore, transcription factor ZNF217 overexpression was observed in the two tumor components and regulated by the hypoxia-inducible factors (HIFs) released by the hypoxic environment of the tumor." (PMID 24649216, 2013).
tumor (continued). "In addition, tumor xenograft models using A549 cells carrying increased levels of miR-199a-3p show reduced tumor growth and stem-like properties, accompanied by elevated apoptosis and impaired mitochondrial function through targeting of the transcription factor ZNF217." (PMID 41154751, 2025). "Despite the high prevalence of ZNF217 mutations, a clear tumor suppressive function of ZNF217 could not be demonstrated." (PMID 37648814, 2023). "In addition to DNA methylation, EPB41L4A-AS2 is also regulated by ZNF217 (zinc finger protein 217)-mediated H3K27me3 (trimethylation of lysine 27 on histone 3), which contributes to inhibited expression of this lncRNA, thus limiting its tumor suppressor activity." (PMID 35865634, 2022). "Thus, we speculate that ZNF217 amplification and/or POLD1 mutations in the tumor may affect overall genome stability and lead to the generation of tumor-specific neoantigens and consequently extensive lymphocyte infiltration." (PMID 35912186, 2022). "ZNF217 overexpression could overcome the repressed cell proliferation, migration and invasion induced by miR-503 in PCa cell lines, whereas knockdown of ZNF217 mimicked the tumor-suppressive effects induced by miR-503 overexpression." (PMID 36551531, 2022). "However, whether the aberrant expression of ZNF217 in regulating iron-related tumor progression remains largely unknown." (PMID 27768596, 2016). "Altogether, evaluating ZNF217 protein biomarker value in tumor samples is complex, and the expected data from future studies dedicated to deciphering the meaning of ZNF217 cytoplasmic localization may help in considering ZNF217 nuclear and/or cytoplasmic signals in translational medicine." (PMID 26431164, 2015). "Interestingly, ZNF217 and GATA3-FOXA1 are associated with opposite tumor phenotypes." (PMID 24962896, 2014). "As with OVCA420 cells, ZNF217 overexpression in TYK-Nu cells also resulted in increased metastasis and tumor burden in Foxn1 nude mice." (PMID 41345234, 2025). "Cluster 0 expressed several tumour-related transcription factors such as ELK4, CREB1, cJun, JunD, KLF6, ETS-1 and ZNF217." (PMID 38480935, 2024). "Tumor sequencing revealed LOH in CHEK2 and PALB2, as well as CCND1,FGFR1, GPR124, ZNF217, ZNF703, and PTPN1 amplifications." (PMID 38091153, 2024). "We observed amplifications in chromosome arm 20q (chr20q) in 74/373 tumours (19.8%), which includes SRC, TOP1, BCL2L1, ZNF217, AURKA, GNAS and ARFRP1." (PMID 37666855, 2023). "In contrast, we show that ZNF217 aberrations in PMBCL often display as deletions and/or truncating frameshift alterations spread all over the coding region suggestive of tumor suppressor properties." (PMID 37648814, 2023). "The miR-200 family represses EMT and tumor invasion by targeting the 3′UTRs of major drivers of EMT, including TGFB, ZEB1 and ZNF217." (PMID 36551531, 2022). "Experimental evidence led to the conclusion that the estrogen-induced miR-503 exerts tumor-suppressive properties in BCa cells, at least in part, by direct targeting of the 3′-UTR of the ZNF217 mRNA." (PMID 36551531, 2022). "Altogether, ZNF217 rescued the oncogenic function of the lncRNA OIP5-AS1, and OIP5-AS1 aggravated EOC tumor progression by sponging miR-137 and upregulating ZNF217." (PMID 36551531, 2022). "Altogether, a signaling axis consisting of lncRNA-ATB/miR-200c/ZNF217/TGF-β2/ZEB1 participates in EMT and tumor progression." (PMID 36551531, 2022). "For example, ZNF545, ZNF569, ZNF383, and ZNF331 are reported to act as tumor suppressor genes, while ZNF147, ZNF217, ZNF278, GLI1, and Evi9 promote tumor progression." (PMID 33566221, 2021).